EPAS1 (endothelial PAS domain protein 1)
Diseases named in the same sentence as EPAS1 in open-access papers (continued):
Sharing a sentence is not in itself a finding about the gene and the disease.
adenoma (3 papers, 2013 to 2021). A neoplasm arising from the epithelium. "Furthermore, the association of EPAS1 mRNA overexpression with associated adenoma indicates its roles in promoting the formation of multiple tumours in patients with CRC." (PMID 34250767, 2021). "Overall, 81% (n = 35/43) of CRC having associated adenoma exhibited high EPAS1 mRNA expression, whereas 59% (n = 23/39) of CRC having no associated adenoma had high EPAS1 mRNA expression (p = 0.02)." (PMID 34250767, 2021). "In addition, 81.4% (n = 35/43) of cancers with associated adenoma showed EPAS1 mRNA overexpression, whereas 59% (n = 23/39) of cancer without associated adenoma CRC had shown EPAS1 mRNA overexpression (p = 0.02)." (PMID 34250767, 2021).
endometriosis (3 papers, 2020 to 2025). The growth of functional endometrial tissue in anatomic sites outside the uterine body. "The expression profiles of key endoplasmic reticulum stress-related genes, including EPAS1, F8, VCAM1, and VWF, exhibited significant disparities between endometriosis specimens and both adjacent normal endometrial tissues and control endometrial tissues." (PMID 41188339, 2025). "The results of bioinformatics analysis suggested that EPAS1, F8, VCAM1, and VWF might be highly expressed in endometriosis." (PMID 41188339, 2025).
esophageal squamous cell carcinoma (3 papers, 2020 to 2022). Esophageal squamous cell carcinoma (ESCC) is a type of esophageal carcinoma (EC) that can affect any part of the esophagus, but is usually located in the upper or middle third. "Correlation of EPAS1 mutations with clinicopathological features of patients with esophageal squamous cell carcinoma." (PMID 33042797, 2020). "Mutations detected in the sequence of EPAS1 in esophageal squamous cell carcinoma." (PMID 33042797, 2020). "Correlation of EPAS1 mRNA expression with clinicopathological features of patients with esophageal squamous cell carcinoma." (PMID 33042797, 2020). "Correlation of EPAS1 DNA variations with clinicopathological features of patients with esophageal squamous cell carcinoma." (PMID 33042797, 2020). "Endothelial PAS domain-containing protein 1 (EPAS1) is an angiogenic factor and its implications have been reported in many cancers but not in esophageal squamous cell carcinoma (ESCC)." (PMID 33042797, 2020).
intestinal tumors (3 papers, 2020 to 2025). "It is tempting to hypothesize that a tumor-promoting effect of fructose might only be observed in Epas1-deficient intestinal tumors." (PMID 32733884, 2020).
Lynch syndrome (3 papers, 2020 to 2023). An autosomal dominant hereditary neoplastic syndrome characterized by the development of colorectal carcinoma and a high risk of developing endometrial carcinoma, gastric carcinoma, ovarian carcinoma, renal pelvis carcinoma, and small intestinal carcinoma. "Mutations in EPAS1 are also noted in patients with Lynch syndrome." (PMID 34250767, 2021). "However, a previous study reported that the complete deletion of EPAS1 associated with Lynch syndrome, a hereditary risk factors for development of CRC." (PMID 34250767, 2021).
medullary thyroid carcinoma (3 papers, 2023 to 2025). "In medullary thyroid carcinoma, inhibition of ZFAS1 also inhibited tumor growth and metastasis through the miR-214-3p/UCHL1/EPAS1 pathway, providing evidence of its role in cancer aggressiveness." (PMID 41154428, 2025).
metastatic carcinoma (3 papers, 2014 to 2022). A carcinoma which has spread from the original site of growth to another anatomic site. "Mutations in EPAS1 sequence correlated with patient's age (p = 0.02) and the presence of metastatic carcinoma in lymph node (p = 0.05)." (PMID 33042797, 2020).
respiratory failure (3 papers, 2014 to 2020). The significant impairment of gas exchange within the lungs resulting in hypoxia, hypercarbia, or both, to the extent that organ tissue perfusion is severely compromised. "One other point of interest is the fact that neonatal mice lacking complete EPAS1 expression have deficient lung surfactant, such as surfactant D (SP-D), in addition to other lung abnormalities and die of respiratory failure." (PMID 25569234, 2015).
sickle cell disease (3 papers, 2024 to 2026). Sickle cell anemias are chronic hemolytic diseases that may induce three types of acute accidents: severe anemia, severe bacterial infections, and ischemic vasoocclusive accidents (VOA) caused by sickle-shaped red blood cells obstructing small blood vessels and capillaries. "Gain-of-function mutations in EPAS1 have been linked to the Pacak-Zhuang syndrome, congenital cyanotic heart disease and sickle cell anaemia." (PMID 41945626, 2026).
stomach cancer (3 papers, 2020 to 2023). "Among autophagy genes in the Reactome database, PRMT1 was negatively correlated with genes such as ATG9A, DYNC1H1, EPAS1, PINK1, TSC1, TUBB6, and ULK1 in gastric tumor tissues (STAD-TCGA) and positively correlated with HMMR, ESCO2, CHAC2, and NUDT6 (STAD-TCGA)." (PMID 37564212, 2023).
Ureteral obstruction (3 papers, 2017 to 2025). Obstruction of the flow of urine through the ureter. "In mice with pro-fibrotic injury induced by ureteral obstruction, upregulation of Tgfb1 was accompanied with downregulation of Epas1 and Epo in injured kidneys and myofibroblasts, which were reversed by ALK5 inhibitor SB431542." (PMID 34724959, 2021).
vascular malformation (3 papers, 2016 to 2024). A non-neoplastic disorder that is the result of defects of vascular morphogenesis. "We discovered vascular malformations due to failure of developmental vascular regression in patients with EPAS1 gain-of-function mutation syndrome and the corresponding transgenic mouse model." (PMID 33497361, 2021). "We identified a spectrum of vascular malformations arising from multifocal irregular vascular development in the EPAS1 gain-of-function syndrome patients as well as the transgenic mouse model." (PMID 33497361, 2021).
virus infection (3 papers, 2017 to 2023). "EPAS1, which is called as HIF-2alpha as well, is induced by hypoxia, playing a key role in virus infection and pro-inflammatory response." (PMID 37949890, 2023).
altitude sickness (2 papers, 2019). Multiple symptoms associated with reduced oxygen at high altitude. "Genomic studies have identified robust signals of positive selection across EPAS1, EGLN1, and PPARA, that are associated with hemoglobin levels, which likely protect the Sherpa from altitude sickness." (PMID 31555147, 2019).
cholangiocarcinoma (2 papers, 2023 to 2024). A carcinoma that arises from the intrahepatic biliary tree (intrahepatic cholangiocarcinoma) or from the junction, or adjacent to the junction, of the right and left hepatic ducts (hilar cholangiocarcinoma). "Fib-C3 cells were like the vascular cancer-associated fibroblasts (vCAFs) in the intrahepatic cholangiocarcinoma and exhibited high expression levels of ACTA2, RGS5, MYH11, and EPAS1." (PMID 39107908, 2024).
Familial erythrocytosis type 4 (2 papers, 2021). "Based on the OMIM and Simple ClinVar databases, EPAS1 is broadly associated with Familial erythrocytosis type 4 (ECYT4), a congenital disease with an excessive erythrocytes mass, elevated hemoglobin, and/or hematocrit." (PMID 34828399, 2021). "Heterozygous variant c.1609G>A in EPAS1 gene is a pathogenic variant that represents an established cause of familial erythrocytosis type 4 (ECYT4, OMIM ID 611783)." (PMID 34349782, 2021).
leiomyosarcoma (2 papers, 2016 to 2022). An uncommon, aggressive malignant smooth muscle neoplasm, usually occurring in post-menopausal women. "Compared to other histological types, leiomyosarcoma showed high expression of HELLS, EPAS1, NQO1 and low expression of IL6." (PMID 34982796, 2022).
myeloid leukemia (2 papers, 2016 to 2022). A clonal proliferation of myeloid cells and their precursors in the bone marrow, peripheral blood, and spleen. "The pathways and genes that significantly changed were classified as follows: cancer pathways (EPAS1, CCND1, FGF13), myeloid leukemia pathways (ZBTB16, KIT, IL13), hematopoietic cell lineage pathways (EPOR, GYPA, CD36) and so on." (PMID 27516205, 2016).
rectal adenocarcinoma (2 papers, 2009 to 2024). "EPAS1 expression was correlated with the levels of CD8+ T cell, macrophages, neutrophils and dendritic cells in rectal adenocarcinoma (READ)." (PMID 37994607, 2024).
tumor predisposition syndrome (2 papers, 2022 to 2025). "The Pacak–Zhuang syndrome is a rare tumor-predisposition syndrome caused by gain-of-function mutations in the gene encoding HIF-2α (EPAS1)." (PMID 40620865, 2025).
amyotrophic lateral sclerosis (1 paper, 2021). Amyotrophic lateral sclerosis (ALS) is a neurodegenerative disease characterized by progressive muscular paralysis reflecting degeneration of motor neurons in the primary motor cortex, corticospinal tracts, brainstem and spinal cord. "EPAS1 is indicative of AD and amyotrophic lateral sclerosis (ALS) in a way that is downregulated and upregulated, respectively." (PMID 33419148, 2021).
autism (1 paper, 2016). Persistent deficits in social interaction and communication and interaction as well as a markedly restricted repertoire of activity and interest as well as repetitive patterns of behavior. "Interestingly, EPAS1 (HIF2), a transcription factor important in the hypoxic response and that interacts with the CH1 domain, was recently identified as a novel autism risk gene." (PMID 26730956, 2016).
Chiari malformation (1 paper, 2019). A rare genetic brain malformation characterized by displacement of the brain stem and cerebellum through the foramen magnum. "Abnormal bone growth of the skull base may lead to Chiari malformation type I. We report two cases of EPAS1 gain-of-function mutation syndrome with Chiari malformation and developmental skull base anomalies." (PMID 31185588, 2019).
Chiari malformation type I (1 paper, 2019). Arnold-Chiari malformation type I is a central nervous system malformation characterized by caudal displacement of the cerebellar tonsils exceeding 5mm below the foramen magnum with or without syringomyelia. "The present study implicates EPAS1 mutations in abnormal posterior fossa development resulting in Chiari malformation type I." (PMID 31185588, 2019). "Herein, we report two patients with EPAS1 gain-of-function mutation syndrome, Chiari malformation type I and other developmental anomalies of the posterior fossa and spine." (PMID 31185588, 2019).
cytomegalovirus infection (1 paper, 2024). A herpesvirus infection caused by Cytomegalovirus. "It has been found that human cytomegalovirus infection inhibited proliferation but promoted VSMC apoptosis by upregulating microRNA-US33-5p, and microRNA-US33-5p bound to the 3’-untranslated region of EPAS1 to suppress its expression, indicating the role of EPAS1 in acute aortic dissection." (PMID 39207146, 2024).
depression (1 paper, 2025). "Upon analyzing the diagnostic model, it was revealed that EPAS1 and IL1R1 serve as key biomarkers for OS in depression, with IL1R1 exhibiting the highest diagnostic potential among them." (PMID 40343008, 2025). "Furthermore, we validated this using a Diagnostic Nomogram, where we assessed the probability of a patient being diagnosed with depression by integrating the scores of the IL1R1 and EPAS1 genes." (PMID 40343008, 2025).
diabetic cardiomyopathy (1 paper, 2024). Diabetic cardiomyopathy is a disorder of the heart muscle in people with diabetes. "Meanwhile, according to previous literature, EPAS1, an endothelial PAS domain protein 1, has been found to have some association with the stability of HCM; MYC is one of the top ten hub genes in diabetic cardiomyopathy (DbCM)." (PMID 38799173, 2024).
endocrine tumors (1 paper, 2022). "Even though several mutations such as VHL, SDHx, EPAS1 and EGLN1 are associated with endocrine tumor initiation, many of these mutations directly or indirectly lead to stabilization of HIFs and consequently triggering the hypoxia pathway." (PMID 36699028, 2022).
glomerular disease (1 paper, 2020). "These and the previous mentioned results show that HIF1α is detrimental, whereas EPAS1/HIF2α confers protection in glomerular disease." (PMID 33123011, 2020).
helminthic infection (1 paper, 2025). "Here we demonstrate that in the intestine, helminthic infection drives accumulation of small intestinal lamina propria Th2 cells marked by elevated expression of the gene Epas1, encoding HIF2α." (PMID 39868305, 2025).
Hereditary Leiomyomatosis and Renal Cell Cancer syndrome (1 paper, 2021). "Newer syndromic PPGL genes include FH (Hereditary Leiomyomatosis and Renal Cell Cancer syndrome), EPAS1 (mainly as a case of germline mosaicism, although EPAS1 mutations are generally more common as somatic mutations) and EGLN1 (associated with congenital polycythaemia)." (PMID 34834591, 2021).
intrauterine growth restriction (1 paper, 2025). "Mutations in EPAS1 (encoding human HIF2A) have a protective effect on high-altitude-associated intrauterine growth restriction and reproductive loss, and HIF2A deficiency in a mouse implantation model revealed a key role in endometrial receptivity, embryonic implantation, and survival." (PMID 39257205, 2025).
itch (1 paper, 2017). "Thus, EPAS1 may be a therapeutic target for controlling IL-31-associated itch." (PMID 28067314, 2017).
liver failure (1 paper, 2022). A liver disease characterized by the liver losing or has lost all of its function. "Seven differentially expressed ferroptosis-related genes (Hmox1, Epas1, Sirt1, Slc3a2, Jun, Plin2 and Zfp36) were obtained through the intersection of ferroptosis-related genes in the FerrDb database with DEGs in the GSE60088 dataset, and all of these genes were up-regulated in liver failure." (PMID 35923893, 2022).
ovarian endometriosis (1 paper, 2025). A non-neoplastic disorder characterized by the growth of endometrial tissue in the ovaries. "A study in 2018 confirmed that EPAS1 expression was significantly upregulated in CD73+CD90+CD105+ pluripotent stem cells isolated from ectopic endometrium compared to paired in situ endometrium, which may be associated with the progression of ovarian endometriosis to associated ovarian cancer." (PMID 41188339, 2025).
pituitary adenomas (1 paper, 2024). "Chiari 1 malformation (CM1) is a rare finding that has been described with growth hormone (GH)-secreting pituitary adenomas and with an endothelial PAS domain protein 1 gain-of-function mutation syndrome." (PMID 38919912, 2024).
placental disorders (1 paper, 2023). "The relevance of EPAS1 to placentation is evident in its association with placental disease." (PMID 37563143, 2023). "To conclude, these predisposing EPAS1 genetic variants associated with pregnancy complications may lead to EPAS1 dysregulation, abnormalities in transcriptional control, and ineffective placentation leading to increased risk of placental disorders." (PMID 37563143, 2023).
pulmonary edema (1 paper, 2022). Accumulation of fluid in the lung tissues causing disturbance of the gas exchange that may lead to respiratory failure. "In additionally, EPAS1 polymorphisms showed associations with reduced susceptibility to high altitude polycythemia and high altitude pulmonary edema in Han populations." (PMID 36244759, 2022).
Stillbirth (1 paper, 2024). Death of the fetus in utero after at least 22 weeks of gestation. "It was also observed that there is a positive correlation between EPAS1 expression and the occurrence of stillbirths." (PMID 39456823, 2024). "In addition, EPAS1 expression is higher in women who have a history of stillbirths in their births." (PMID 39456823, 2024). "Taking into account the increased expression of EPAS1 in women with a history of stillbirth, the measurement of HIF-2α during pregnancy could have a diagnostic role and allow the selection of a group of women at risk of stillbirth, which may result in providing specialized care to such patients." (PMID 39456823, 2024). "Expression of the EPAS1 gene was more than three times higher in the material collected from women with a history of stillbirths in previous pregnancies than in the cellular fraction of milk collected from women without a history of stillbirths (p = 0.001)." (PMID 39456823, 2024).